ZNF544 (zinc finger protein 544)
Description:
May be involved in transcriptional regulation.
Synonyms: AF020591
Tractability: PROTAC: UniProt records ubiquitination sites on it; ubiquitination databases record sites on it.
Gene: Protein-coding gene on chromosome 19 (58,228,594 to 58,277,495, forward strand). Ensembl gene ENSG00000198131.
Subcellular location: Nucleus
Subcellular location (Human Protein Atlas): Nucleoplasm
Pathways (Reactome):
Gene expression (Transcription): Generic Transcription Pathway
Gene Ontology:
Molecular function: protein binding; transcription cis-regulatory region binding
Biological process: regulation of transcription by RNA polymerase II; regulation of DNA-templated transcription
Cellular component: nucleus
Genetic constraint (gnomAD): Loss-of-function variants: 10 observed, 14.39 expected, observed/expected ratio (o/e) 0.69, 90% interval 0.43 to 1.18. The upper end of that interval is the gene's LOEUF score, 1.18, which puts it in group 5 of 6, group 1 being the genes least tolerant of losing a copy. Missense variants: 896 observed, 883.5 expected, observed/expected ratio (o/e) 1.01, 90% interval 0.96 to 1.07. Synonymous variants: 323 observed, 313.87 expected, observed/expected ratio (o/e) 1.03, 90% interval 0.94 to 1.13.
Homologues: Orthologues: pig ZNF544 (62% identical). Paralogues in human: ZNF879 (30% identical), ZNF717 (29% identical), ZNF182 (29% identical), ZNF585B (29% identical), ZNF30 (29% identical), ZNF484 (29% identical), ZNF606 (29% identical), ZNF471 (29% identical), ZNF250 (29% identical), ZNF41 (29% identical), ZNF658 (29% identical), ZNF7 (29% identical), and 164 more.
Diseases named in the same sentence as ZNF544 in open-access papers:
ZNF544 is named in the same sentence as 2 diseases in open-access papers, as found by Europe PMC text mining. Sharing a sentence is not in itself a finding about the gene and the disease. The quoted sentences say what the papers report.
breast carcinoma (1 paper, 2021). "High expression of ZNF644 might be associated with the radiosensitivity of breast cancer patients, and reciprocally, low expression of the other 3 genes (ZNF341, ZNF544, and ZNF653) marked patients in the radiosensitive group." (PMID 34504527, 2021).
ZNF544 also shares sentences with these, for which no sentence is quoted: endometrial cancer (1 paper).